ALB (albumin)
Diseases named in the same sentence as ALB in open-access papers (continued):
Sharing a sentence is not in itself a finding about the gene and the disease.
malnutrition (continued). "Given that hypoalbuminemia may result from a combination of malnutrition and inflammatory processes, our work is consistent with the literature suggesting that albumin cutoff values might be overly simplistic." (PMID 41228270, 2025). "Additionally, we utilized the three most recognized laboratory parameters for malnutrition—albumin, transferrin, and lymphocytes—enabling evaluation of each criterion's individual and combined effectiveness." (PMID 40727701, 2025). "A decline in albumin levels often indicates malnutrition and a chronic inflammatory state." (PMID 40709341, 2025). "After adjusting for potential confounders—including BMI, GLIM criteria for malnutrition, procalcitonin levels, albumin levels, and the Charlson comorbidity index at admission—sarcopenia remained a significant predictor of mortality, with an HR of 2.95 (95% CI: 1.03–8.46; p = 0.04)." (PMID 40725756, 2025). "Reduced levels of albumin typically signify malnutrition, which may result from an inadequate diet, chronic diseases, or inflammatory processes." (PMID 40860484, 2025). "Given that RAR combines RDW, which reflects erythrocyte variability and systemic inflammation, with albumin, which indicates malnutrition, it may be particularly sensitive for predicting short-term mortality risk, such as 1-year mortality." (PMID 41229545, 2025). "Short survivors had significantly lower mean albumin (3.1 vs. 3.5 g/dL, p < 0.001), transferrin (156.6 vs. 186.6 mg/dL, p < 0.001) and total cholesterol levels (151.2 vs. 164.0 mg/dL, p = 0.003), indicating a possibly more pronounced state of malnutrition." (PMID 40077616, 2025). "In the subsequent comparison of nutritional status, the experimental group showed an increase in ALB, HGB, and TP, as well as a reduced risk of malnutrition, demonstrating that FA is also of great significance in improving the nutritional status of AD patients." (PMID 41281281, 2025). "In malnutrition, the decrease in albumin level not only indicates insufficient reserve, but also may affect the body’s metabolism and organ function, and further aggravate nutritional deterioration." (PMID 41568390, 2025). "The CRP/ALB ratio may, therefore, be a useful marker for assessment of critically ill patients, as it effectively reflects both inflammation and malnutrition." (PMID 40573094, 2025). "For the assessment of malnutrition, the Geriatric Nutritional Risk Index (GNRI) could also be used if serum albumin, height, and weight are available." (PMID 40364892, 2025). "However, the prognostic value of the serum albumin level as an indicator of malnutrition is questioned, among others, due to the variability of its concentration in various disease states." (PMID 41476191, 2025). "These factors, including malnutrition, low serum albumin, overweight, and anemia, may contribute to exacerbated or poorly controlled asthma symptoms through mechanisms such as exacerbation of chronic inflammation and immune response." (PMID 39980673, 2025). "However, the level of albumin in the serum can be affected by various factors, such as inflammation, malnutrition, and cancer cachexia, leading to a condition called hypoalbuminemia." (PMID 40095884, 2025). "However, when albumin levels decrease, in response to various conditions (e.g., liver disease, malnutrition, or inflammation), the oncotic pressure is reduced, promoting the leakage of fluid into the interstitial space, which ultimately results in edema." (PMID 41440732, 2025). "While clinicians often rely on NT-proBNP as a mainstay biomarker, albumin’s parallel reflection of nutritional and inflammatory states can provide additional prognostic context—particularly in clinical settings where malnutrition, systemic inflammation, or hepatic congestion are prevalent." (PMID 41007652, 2025). "Albumin is a marker reflecting malnutrition and systemic inflammation in critically ill patients." (PMID 40142349, 2025).
malnutrition (continued). "According to the 2024CSCO guidelines for esophageal cancer, artificial nutrition is recommended for patients with malnutrition (weight loss within 6 months) >10%, BMI<18.5kg/m2, or serum albumin <30g/L in patients without liver dysfunction." (PMID 40626016, 2025). "Serum albumin levels were assessed in 5 studies as a marker of malnutrition." (PMID 40384608, 2025). "In this vein, it has been argued that malnutrition (and consequently a reduced bioavailability of protein) leads to a reduced protein synthesis including albumin- and hemoglobin synthesis which may in turn affect the hematopoiesis." (PMID 40836330, 2025). "Moreover, we just chose the albumin level and BMI to assess malnutrition because other information, such as bioelectrical impedance, midarm muscle circumference, and muscle mass was not available." (PMID 40225113, 2025). "Notably, when using serum albumin or total cholesterol to define malnutrition, prevalences of malnutrition were significantly different (70.2 vs. 3.8%)." (PMID 40785303, 2025). "In addition, compared with CAR, UAR and albumin, two inflammatory and one malnutrition parameter, respectively, this study revealed better discriminatory power of ALI than these parameters." (PMID 40094797, 2025). "While several studies have focused on preoperative hypoalbuminemia, serum albumin levels may decrease following trauma, malnutrition, major surgery, or severe infection." (PMID 41303773, 2025). "HD patients with elevated serum CRP and reduced albumin levels are often described as having malnutrition–inflammation–atherosclerosis syndrome, which highlights the association between these factors and the progression of advanced atherosclerotic cardiovascular disease." (PMID 41149851, 2025). "Moreover, insufficient nutrition is considered a risk factor for osteoporosis, and some studies suggest that prealbumin is more suitable than albumin as a malnutrition biomarker." (PMID 41480543, 2025). "We identified notable correlations between decreased eGFR and low serum albumin, low HDL-cholesterol, high triglycerides, and low MNA score, emphasizing that malnutrition was also significantly associated with more advanced kidney disease in the enrolled patients." (PMID 40566551, 2025). "Specifically, diminished albumin levels may reflect severe comorbidities (Acute inflammation, infection, liver disease, or vascular endothelial injury) or malnutrition, both of which contribute to poor prognoses." (PMID 40534743, 2025). "Albumin reflects the nutritional status, and malnutrition decreases the serum albumin level." (PMID 39976660, 2025). "Albumin levels were very low (mean 17.2 g/L), indicating severe malnutrition." (PMID 41323009, 2025). "Albumin levels can reflect the nutritional status and immune function in animals, and low levels may indicate malnutrition or impaired immune function." (PMID 40520430, 2025). "However, it should be noted that MM, PhA, and serum albumin were significant protective markers against malnutrition in the regression model." (PMID 41228397, 2025). "Low albumin levels oftenreflect either malnutrition or heightened inflammatory responses." (PMID 40351679, 2025). "Similarly, belonging to the group at risk of malnutrition, as expressed in the MNA scale, can help predict a decrease in serum albumin (p < 0.01)." (PMID 40944175, 2025). "Moreover, other studies found that a low albumin level in hemodialysis patients is a strong predictor that reflects malnutrition." (PMID 39854402, 2025). "Low albumin levels often signify malnutrition, systemic inflammation, or liver dysfunction." (PMID 40725602, 2025). "The prevalence of malnutrition as per MNA-SF was 59% and it is linked with BMI and serum albumin." (PMID 40837918, 2025). "Of patients with malnutrition risk, those who also exhibited frailty were older and more likely to have cognitive impairment, dyslipidemia, and lower BMIs and hemoglobin and albumin levels compared to those without frailty." (PMID 39861351, 2025).
malnutrition (continued). "Finally, we explored the moderating effect of urinary albumin on the relationship between CC and malnutrition." (PMID 41440732, 2025). "Albumin concentrations decrease in older adults with severe malnutrition." (PMID 41041271, 2025). "It is reported that low level of albumin was related to malnutrition, however the relationship between ΔAlb and malnutrition remains unclear." (PMID 40432957, 2025). "In this case, advanced age (79 yrs), malnutrition (potassium at 3.10 mmol/L and albumin at 39.3 g/L), and specific anatomical regions (left pelvis) may be contributing factors to Mycoplasma hominis infections." (PMID 39931564, 2025). "Albumin and TC levels are well‐known indicators of malnutrition." (PMID 39631788, 2025). "Studies have shown that insufficient dietary diversity (few daily food types), insufficient intake of energy and high-quality protein were directly related to postoperative malnutrition, while BMI, serum albumin, and pre-albumin are key indicators reflecting the body's nutritional reserve." (PMID 41220716, 2025). "Albumin, a protein that exerts important homeostatic effects, including maintaining osmotic colloid pressure, intravascular transport of molecules, and lipid metabolism, is classically considered a biomarker of malnutrition and poor health status." (PMID 40399692, 2025). "Analysis of the visceral proteins—albumin and prealbumin—revealed that reduced levels were present not only in the “high-risk” malnutrition cohort but also in patients without restricted food intake and weight loss." (PMID 40944259, 2025). "ALB can help to maintain fluid balance in the body, and low concentrations may suggest malnutrition or liver dysfunction, which can affect stroke outcomes." (PMID 40463589, 2025). "For instance, depleted albumin levels may be emblematic of malnutrition, detracting from post-surgical recovery potential." (PMID 40034601, 2025). "Therefore, inflammation is an essential factor in the development of malnutrition, as indicated by markers such as albumin, prealbumin, and C-reactive protein (CRP)." (PMID 40094974, 2025). "The fourth quartile (Q4) showed lower survival than Q2–Q3 but higher survival than Q1, which may be attributed to a smaller proportion of patients with severe malnutrition (higher albumin levels) compared to Q1, despite elevated neutrophil counts." (PMID 40969605, 2025). "However, in the present study, a serum albumin concentration below 3.0 g/dL occurred in most patients diagnosed with severe malnutrition." (PMID 40094974, 2025). "Moreover, low albumin levels and malnutrition affect the adverse effects of anti-TNF administration, as does corticosteroid use." (PMID 41155581, 2025). "The low ALB level may have been significant for DFS because ALB levels reflect malnutrition, inflammation, and immune status better than ALP levels." (PMID 39941572, 2025). "A low serum albumin is indicative of malnutrition and inflammation, which are both common in cancer patients, while a reduced lymphocyte count might reflect immune system suppression." (PMID 41228489, 2025). "Moreover, cancer patients on dialysis exhibit markers of malnutrition (lower albumin, hemoglobin, lean mass) and laboratory anomalies, which point to inflammation (higher ferritin, lower phosphorus)." (PMID 40940879, 2025). "Therefore, this study aimed to investigate the correlation between preoperative malnutrition, based on albumin level and BMI, and operative outcomes, short-term prognosis, and complications in CRLM patients who underwent hepatectomy." (PMID 40225113, 2025). "Patients with ΔAlb ≥ 16% were more likely to be female (p = 0.033), had higher preoperative hemoglobin (p = 0.019) and albumin levels (p < 0.001), and more prevalence of malnutrition (p = 0.03), but lower BMI (p = 0.002) and skeletal muscle index (SMI) (p < 0.001) compared to those with ∆Alb < 16%." (PMID 40432957, 2025).
malnutrition (continued). "A grounding in nutrition may afford surgeons the ability to observe for ‘soft markers’ of malnutrition, while those that have less exposure rely on ‘objective’ markers like albumin." (PMID 40230316, 2025). "Other nutritional parameters that may reflect a state of malnutrition include serum albumin and lymphocyte count, either alone or as a combined score (the prognostic nutritional index, PNI), which is a marker of both nutritional and inflammatory status." (PMID 40458822, 2025). "Both ALB as well as TP blood levels, considered nutritional laboratory markers for malnutrition, were found to be within a similar range (TP: 41–55 g/L; ALB: 31–44 g/L) for all cohorts evaluated, which supports a healthy nutrition of all animals from the experiment." (PMID 39392495, 2025). "Additionally, TNF‐α selectively inhibits the gene expression of albumin, playing a critical role in the development of malnutrition in pancreatic cancer." (PMID 40631494, 2025). "Decreased albumin levels could indicate malnutrition, which is a possible explanation considering the decreased body weight in SHR+DM." (PMID 40698664, 2025). "Notably, when using serum albumin < 3.8 g/dL or total cholesterol < 100 mg/dL to define malnutrition, malnutrition prevalences were 70.2 and 3.8%, respectively." (PMID 40785303, 2025). "Albumin, a negative acute-phase protein synthesized in the liver, and reduced levels of it is associated with malnutrition, inflammation, and metabolic changes caused by cancer cells." (PMID 40365347, 2025). "Besides, both malnutrition and albumin levels emerged as independent prognostic factors for end-stage kidney disease mortality during a 10-year follow-up." (PMID 40013151, 2025). "Nevertheless, further explanations for our findings regarding the protective effect of low albumin levels against malnutrition may include confounding factors, which might influence the association and mask the link between low albumin and malnutrition." (PMID 39854402, 2025). "To date, malnutrition has primarily been analyzed using composite laboratory scores, such as the CONUT score, Geriatric Nutritional Risk Index (GNRI), Prognostic Nutritional Index (PNI), and HALP score (Hemoglobin, Albumin, Lymphocyte, and Platelet score)." (PMID 40077787, 2025). "In scientific reports, the concentrations of albumin, hemoglobin, total cholesterol, prealbumin, and total protein were found to be lower in malnourished individuals than in those without malnutrition risk." (PMID 40094974, 2025). "Serum albumin is commonly used as a biochemical marker for evaluating nutritional status; reduced albumin levels may indicate malnutrition or compromised health." (PMID 41180526, 2025). "Furthermore, malnutrition, indicated by low albumin levels, contributes to muscle wasting, impaired immune responses, and heightened infection susceptibility, elevating all-cause mortality risk." (PMID 41254862, 2025). "Decreased serum albumin levels reflect malnutrition and inflammation." (PMID 40095849, 2025). "Moreover, our observation that lower serum albumin levels significantly portend worse outcomes aligns with the concept that systemic inflammation, malnutrition, and hepatic congestion collectively weaken the clinical trajectory in CHF." (PMID 41007652, 2025). "HD patients with mild protein-energy wasting, defined as a serum albumin level of 3.5–3.9 mg/dl despite 7-point subjective global assessment in category A or a malnutrition inflammation score ≤5, were randomly assigned to receive IDAA by continuous infusion or acute load for 3 months." (PMID 40008349, 2025). "We observed a significantly lower albumin level in the blood of PTC patients compared to the control, which may be associated with the malnutrition and inflammation that occur during the course of the cancer." (PMID 39145825, 2025). "If we had incorporated malnutrition-related factors such as albumin and lymphocyte count, the results might have been improved." (PMID 40807041, 2025).
malnutrition (continued). "General epidemiological studies and recent studies in PDAC have shown that low albumin levels are a negative prognostic factor associated with malnutrition." (PMID 39852142, 2025). "Lowered ALB levels suggest malnutrition, inflammatory activation, and compromised liver function." (PMID 40630492, 2025). "In addition, when using serum albumin < 3.8 g/dL or total cholesterol < 100 mg/dL to define malnutrition, malnutrition prevalences were 70.2 and 3.8%, respectively." (PMID 40785303, 2025). "Nutritional deficiencies can cause an increase in RDW and a decrease in albumin." (PMID 40168268, 2025). "Cholinesterase may be less influenced by inflammation than albumin and is considered to be a more reliable indicator of malnutrition." (PMID 39570570, 2024). "However, traditional malnutrition indices, such as albumin levels or BMI, are often affected by the disease itself." (PMID 39728053, 2024). "GNRIs are calculated by combining albumin and body mass index (BMI) values and may underestimate malnutrition in individuals with normal or excessive BMI." (PMID 39339776, 2024). "Low albumin levels could indicate a heightened inflammatory response or malnutrition, both of which are known to adversely affect melanoma prognosis." (PMID 39600700, 2024). "Malnutrition was categorized based on the cutoff value of 4.0 g/dL in albumin analysis." (PMID 38836831, 2024). "Anemia can be a manifestation of malnutrition, which, in turn, may lead to decreased levels of albumin." (PMID 38549094, 2024). "A decrease in serum albumin levels could suggest that the individual is suffering from malnutrition, which can have adverse effects on their overall physical condition." (PMID 39015497, 2024). "The study found significant reductions in serum CRP and IL-6 levels, indicating decreased systemic inflammation, along with improvements in serum albumin, the upper-arm circumference, and the triceps skinfold thickness, partially improving malnutrition and quality of life." (PMID 39457689, 2024). "It is often used as a marker for malnutrition and has a shorter half-life (2–3 days) compared to albumin; hence, it may be more useful as an indicator of recent poor nutritional intake." (PMID 39125374, 2024). "Inflammation may also contribute to malnutrition, leading to a decrease in total protein and albumin levels in the CKD population." (PMID 38610612, 2024). "Moreover, ALB has long been used as a representative marker of malnutrition; however, serum ALB levels are easily affected by inflammation, and therefore, serum ALB and C-reactive protein (CRP) levels are known to be negatively associated with each other." (PMID 39519547, 2024). "First, malnutrition can greatly affect postoperative outcome among gastric cancer patients, while our patients with MetS alone experienced a better nutritional status, manifested as better albumin, hemoglobin, NRS2002 score, and body compositions." (PMID 39315666, 2024). "A recent study also reported that serum transferrin and prealbumin may outperform albumin in identifying patients with esophageal cancer with malnutrition and poor prognosis." (PMID 38438901, 2024). "The lack of IFN-γ signaling also caused liver dysfunction and malnutrition, as evidenced by decreased serum albumin (ALB) and glucose (GLU) levels." (PMID 38743761, 2024). "While low albumin levels may potentially lead to cognitive impairment, a reverse causation is also plausible, where cognitive impairment could result in malnutrition and subsequent albumin reduction." (PMID 39114530, 2024). "Meanwhile, the synthesis of albumin is influenced by chronic inflammation and malnutrition, and lower levels of albumin may be a marker of continuous arterial injury, as well as the progression of atherosclerosis and thrombosis." (PMID 38571747, 2024). "Furthermore, a review of studies on patients with CLTI reported that low serum albumin levels, used as a marker of malnutrition, were related to increased mortality." (PMID 39682536, 2024).